ATR (ATR checkpoint kinase)
Diseases named in the same sentence as ATR in open-access papers (continued):
Sharing a sentence is not in itself a finding about the gene and the disease.
Ewing sarcoma (15 papers, 2012 to 2025). A small round cell tumor that lacks morphologic, immunohistochemical, and electron microscopic evidence of neuroectodermal differentiation. "The increase in R-loops, in turn, causes ATR activation, and similar to Ewing sarcoma, cells expressing mutant U2AF are sensitive to ATR inhibition." (PMID 37108225, 2023). "Ewing sarcoma cells contain an increased burden of R-loops due to the mechanism underlying their tumorigenicity and are therefore highly sensitive to ATR inhibition." (PMID 37108225, 2023). "Ewing tumors have been previously shown to harbor elevated levels of endogenous DNA damage, elevated levels of replication stress (RS) and sensitivity to ATR and CHK1 inhibitors." (PMID 35220396, 2022). "We found that, upon DDK inhibition, there was a slight but consistent increase in the pCHK1-S345 (ATR-dependent phosphorylation) in the Ewing sarcoma cells especially at later time points (>8 h) but not in U2OS." (PMID 35220396, 2022). "Sensitivity of ARMS cells to ATR pathway inhibition was similar to that of Ewing sarcoma cell lines, which were reported to be hypersensitive to ATR inhibition due to fusion oncogene-induced replication stress." (PMID 35879366, 2022). "In this study, combination treatments of the HSP90 inhibitor AUY922 with either the ATR inhibitor VE821 or the ATM inhibitor KU55933 were investigated for their effectiveness in Ewing's sarcoma cells." (PMID 33743824, 2021). "We identified that the combination of gemcitabine with a CHK1 inhibitor (LY2603618) was more effective at inhibiting Ewing sarcoma cell growth than the combination of gemcitabine with an ATR inhibitor (AZ20)." (PMID 29152060, 2017). "Treatment of Ewing sarcoma cells with gemcitabine results in the activation of CHK1 via ATR, which is a well-established upstream regulator of CHK1." (PMID 29152060, 2017). "As predicted, we also showed that Ewing sarcoma cells are sensitive to short (6-hour) drug treatments with gemcitabine in combination with an ATR inhibitor (AZ20)." (PMID 29152060, 2017). "We here provide evidence of a distinctively high sensitivity of Ewing sarcomas to ATR inhibitors, which correlates with high levels of endogenous RS in these tumors." (PMID 27577084, 2016). "Our data shed light onto the sensitivity of ES to genotoxic agents, and identify ATR inhibitors as a potential therapy for Ewing Sarcomas." (PMID 27577084, 2016). "Our study reveals that combined targeting of ATR and RNR was effective against Ewing’s sarcoma in vitro and thus rationalises an in vivo exploration into the potential of combining ATR and RNR inhibitors as a new strategy for the treatment of this challenging disease." (PMID 37097390, 2023). "In addition to ATR inhibitors, Ewing sarcoma cells are quite vulnerable to transcription blockade through Topoisomerase and PARP inhibitors as well." (PMID 37108225, 2023). "Moreover, in a panel of human Ewing's sarcoma family tumor cells, sublethal concentrations of bortezomib (proteasome inhibitor) or VE‐821 (ATR inhibitor) induced cell death when combined with FGF2." (PMID 30422399, 2019). "Based on the increased level of replication stress in Ewing sarcoma cells and the known sensitivity of Ewing sarcoma cells to ATR inhibitors, we tested a CHK1 inhibitor (LY2603618) as a single agent to evaluate the effect of inhibition of CHK1 on the viability of Ewing sarcoma cells." (PMID 29152060, 2017). "Collectively, these data reveal the presence of RS in Ewing sarcomas suggesting that these tumors could be particularly responsive to ATR inhibitors." (PMID 27577084, 2016). "Consequently, the toxicity of ATR inhibitors as single agents with Ewing sarcoma cells may, in part, be due to inhibition of RNR by reducing levels of the RRM2 subunit." (PMID 29152060, 2017). "The present study was conducted to explore the effectiveness of combined inhibition of two promising targets, ATR and ribonucleotide reductase (RNR), in Ewing’s sarcoma cells." (PMID 37097390, 2023).
Ewing sarcoma (continued). "Consistent with the effect of inhibition of ATR on the activation of CHK1, the ATR inhibitor significantly reduced Ewing sarcoma cell growth in combination with gemcitabine." (PMID 29152060, 2017). "DNA repair is dependent on DNA damage response pathways, particularly through ataxia telangiectasia and Rad3-related protein (ATR), which is activated in response to replication stress, a notable feature of Ewing sarcoma through EWS-FLI1-mediated increased transcription." (PMID 38775200, 2024). "In particular, fusion-positive Ewing sarcoma cells (A673 and TC32) exhibit exquisite sensitivity to THZ531, a CDK12/13 inhibitor, resulting in the downregulation of the homologous recombination (HR) and DNA damage checkpoint genes, including BRCA1, ATR, FANCl, and FANCD2." (PMID 40760094, 2025).
small cell lung carcinoma (15 papers, 2017 to 2025). Small cell lung cancer (SCLC) is a highly aggressive malignant neoplasm, accounting for 10-15% of lung cancer cases, characterized byrapid growth, and early metastasis. "One study showed that ATRi with small molecule inhibitors or ATR-targeted siRNA augmented expression of PD-L1 in murine and human small cell lung cancer (SCLC) cell lines via the cGAS/STING pathway." (PMID 41417226, 2025). "We found that the DNA damaging RNA Pol‐II inhibitor lurbinectedin strongly synergizes with the ATR inhibitor berzosertib in small cell lung cancer." (PMID 37491889, 2023). "In addition, uniquely in this study belotecan, a novel topoisomerase I inhibitor, which is a Korean FDA-approved anticancer drug in ovarian or small cell lung cancer, was tested in combination with ATR inhibitor." (PMID 33513721, 2021). "Hence, the ATR/Chk1 pathway is a novel pathway that could be explored for anticancer therapy development in small-cell lung cancer." (PMID 37762228, 2023). "Inhibition of ATR and TOP1 is reported to augment the immunogenicity of small-cell lung cancer." (PMID 40282196, 2025). "A randomized phase 2 clinical trial of patients with small-cell lung cancer treated with ATR inhibitor berzosertib plus topotecan did not improve progression-free survival compared with topotecan therapy alone among patients with relapsed SCLC." (PMID 38255825, 2024). "The ATR/CHK1 (the downstream effector kinases of ATR) axis was identified as a potential drug target for small-cell lung cancer (SCLC) patients, but no similar study in NSCLC has been reported." (PMID 34195081, 2021).
triple-negative breast carcinoma (15 papers, 2018 to 2025). An invasive breast carcinoma which is negative for expression of estrogen receptor (ER), progesterone receptor (PR), and human epidermal growth factor receptor 2 (HER2). "Similarly, dual targeting of BUB1 with ATR or PARP inhibitors yields synergistic activity against triple-negative breast cancer cells." (PMID 40180891, 2025). "Similarly, the depletion of either MMS19 or CIA2B sensitizes triple-negative breast cancer cells to treatment with inhibitors of ATR or CHK1 proteins." (PMID 40136691, 2025). "Indeed, it has already been observed that dysfunctions in the CIA complex sensitize triple-negative breast cancer cells to ATR and CHK1 inhibitors." (PMID 40136691, 2025). "In a recent study using patient-derived xenograft models of triple-negative breast cancer, lartesertib in combination with the ATR inhibitor gartisertib led to a substantially improved tumor control rate compared with single-agent gartisertib (42% vs. 27%; 17)." (PMID 40875525, 2025). "In triple-negative breast cancers, ATR inhibitors are highly efficient in patient-derived xenografts that have a BRCA1 mutation or that exhibit the BRCA-like phenocopy when combined with irinotecan, a clinically approved topoisomerase 1 inhibitor that causes double-stranded breaks." (PMID 32997669, 2020). "We evaluated whether ATR signaling has clinical significance and could be targeted by synthetic lethality in PTEN-deficient triple-negative breast cancer (TNBC)." (PMID 29396668, 2018). "In triple-negative breast cancer (TNBC), ATR inhibition combined with LBH depletion increased DNA replication stress and cell death." (PMID 40256842, 2025). "Interestingly, the ATR inhibitor AZD6738 is in clinical trials in combination with olaparib in triple-negative breast cancer, suggesting that the effects of PARP inhibitors in combination with ATR inhibitors could be tested in patients with ATM-deficient tumours." (PMID 31481733, 2019). "The same trial also terminated the concurrent olaparib plus ceralasertib arm due to no additional benefit with the addition of ATR inhibitor over PARP inhibitor alone in acquired platinum resistance triple negative breast cancer." (PMID 40442403, 2025).
viral infection (14 papers, 2014 to 2026). "Together, these results imply that in addition to viral infection, DNA damage is another cause of stress leading to the upregulation of A3A expression and ATR activation is important in protecting our cells against DNA damage-induced A3A expression." (PMID 34389714, 2021). "Previous studies have revealed that ASFV could elicit the Ataxia Telangiectasia mutated and Rad3-related protein-Checkpoint kinase 1 (ATR-Chk1) pathway, which is required for successful viral infection of host cells." (PMID 33374251, 2020). "The ATM—Chk2 pathway principally responds to DNA double-strand breaks, whereas the ATR—Chk1 pathway responds to a broad range of DNA abnormalities caused by ultra-violet light, DNA replication block, virus infection, interstrand DNA crosslinking, and double-strand break end resection." (PMID 26727128, 2016). "In contrast, KRASG12V/+ cells exhibited hypersensitivity to inhibitors for the ATR-Chk1 checkpoint signalling axis and to nucleoside analogues commonly used to treat cancers and viral infections." (PMID 41750275, 2026). "Moreover, hnRNP UL1 is required for ataxia telangiectasia and Rad3-related protein (ATR)-dependent signaling in response to viral infection 2,26." (PMID 35982897, 2022). "RNAseq and protein expression analysis ofDDB2,RAD17,PRKDC,PCNA and other ATR pathway markers of infected cells accompanied by time course studies of nascent double stranded chromosomal breaks (i.e. H2AX antibody staining due to viral infection) would provide such evidence." (PMID 33299552, 2020). "Focusing on MCPyV, it has been demonstrated that viral infection activates both the ATM and ATR arms of DDR, while MCPyV LT expression alone predominantly activates ATR, suggesting that MCPyV oncoproteins act synergistically to drive carcinogenesis." (PMID 40399437, 2025). "Taken together, these findings suggest that although ATR signaling is inactivated by MVM infection at late stages, it is required at the early stages of the viral infection to initially establish APAR bodies." (PMID 37376543, 2023). "Since E4orf4 appears to inhibit the ATM- and ATR-regulated DDR and DDR was suggested to be detrimental to Ad infection, we examined the contribution of E4orf4 and the DDR components ATM and ATR to the efficiency of virus infection." (PMID 26867009, 2016). "Our results together with the lengths to which Ad goes to inhibit ATM and ATR signaling, strongly suggest that both ATM and ATR can inhibit Ad replication, at least under some conditions, and that their elimination is therefore important for efficient virus infection." (PMID 26867009, 2016). "Viral infection by BKPyV did cause severe DNA damage in the absence of ATM or ATR, and as previously noted, numerous animal and plant studies have shown that ATM and ATR play central roles in DNA damage repair." (PMID 24699527, 2014).
lung adenocarcinoma (12 papers, 2017 to 2025). A carcinoma that arises from the lung and is characterized by the presence of malignant glandular epithelial cells. "If ATR undergoes mutations or exhibits abnormal functionality, it will result in the disruption of the regulatory mechanisms governing cell proliferation, thereby posing a latent risk for the development of lung adenocarcinoma." (PMID 40282196, 2025). "These gene mutations may be secondary somatic mutations based on germline ATR c.7667C>G (p.T2556S) mutations, which eventually lead to the occurrence and progression of lung adenocarcinoma." (PMID 35712480, 2022). "The population frequency in the entire population is 0.0399361 percent, suggesting that this ATR germline mutation may be a genetic susceptibility factor for lung adenocarcinoma." (PMID 35712480, 2022). "In view of this, we have reason to believe that germline ATR c.7667C>G (p.T2556S) mutation may lead to familial clusters of lung adenocarcinoma and differentially expressed ATR may play an essential role in the occurrence and development of lung adenocarcinoma." (PMID 35712480, 2022). "The underlying mechanism of ATR expression in lung adenocarcinoma requires further study, hence we analyzed ATR related expression and prognosis in cases of lung adenocarcinoma." (PMID 35712480, 2022). "Somatic mutations of multiple MMR genes as well as POLE, POLQ, ATM, and ATR were significantly associated with higher neoantigen loads in UCEC, BRCA, lung adenocarcinoma (LUAD), and STAD (FDR < 1.2 × 10−5)." (PMID 34095878, 2021). "Then, we analyzed the expression and prognosis of ATR in lung adenocarcinoma." (PMID 35712480, 2022). "Furthermore, we employed single-cell sequencing data to investigate the expression of ATR in lung adenocarcinoma cell types." (PMID 35712480, 2022). "Interestingly, ATM/ATR was induced more strongly by γ-rays at 1 Gy than by C-ions (LET 290 keV/μm) at 4 h post-irradiation in lung adenocarcinoma A549 cells." (PMID 34681703, 2021). "Importantly, four of the top ten pathways (pathways with ranks 1, 2, 6 and 10) are associated with genes identified as either therapeutic targets for lung adenocarcinoma (Ran and ATR) or as biomarkers of patient prognonsis (CDC6)." (PMID 30541428, 2018). "The research findings indicate that ATR, RFC4, and MCM2 are pivotal genes in the pathogenesis of type 2 diabetes and lung adenocarcinoma." (PMID 40282196, 2025). "We deleted ATM from A549 lung adenocarcinoma cells using CRISPR/Cas9 and determined the effects of olaparib and the ATM/Rad3-related (ATR) inhibitor VE-821 on cell viability." (PMID 31481733, 2019). "We further demonstrate that murine SCLC tumors were highly sensitive to ATR- and CHK1 inhibitors, while KrasG12D-driven murine lung adenocarcinomas were resistant against these compounds and displayed continued growth under therapy." (PMID 29138515, 2017). "However, low- and high-LET irradiation elicit quite different DDRs: for instance, in lung adenocarcinoma A549 cells, C-ions (LET 290 keV/μm) at 1 Gy induced ATM/ATR activation more strongly than γ-rays at 4 h post-irradiation." (PMID 34681703, 2021). "Previous studies have reported that heterozygotes for the ATR gene, which reduce ATR protein expression to about half, are tumor-prone because of partial DDR defects leading to GIN that accelerate the incidence of lung adenocarcinoma induced by oncogenic KRASG12D." (PMID 39456601, 2024). "Both, ATR- and CHK1 inhibitors induce genotoxic damage and apoptosis in human and murine SCLC cell lines, but not in lung adenocarcinoma cells." (PMID 29138515, 2017).
bladder cancer (11 papers, 2016 to 2025). "CDC6 has also been reported to be associated with cisplatin resistance by activation of ATR-Chk1 pathway in bladder cancer cells." (PMID 32792963, 2020). "ATR mutations are most frequently found in endometrial carcinoma (~12.1%), followed by melanoma (~11.7%) and bladder cancer (~7.5%)." (PMID 33224881, 2020). "In the clinical microarray profile, high ATR expression is associated with poor prognosis in bladder cancer patients who receive chemotherapy." (PMID 26657501, 2016). "Drug interaction mapping identified nine target genes (e.g., DAPK1, ATR, and MTR) associated with eight FDA-approved bladder cancer therapies, including cisplatin and gemcitabine." (PMID 40940866, 2025). "First, our findings cannot simply be extended to all bladder cancer cells, despite our investigation of the effects of pharmacological ATR inhibition in three bladder cancer cell lines that represent bladder cancer heterogeneity." (PMID 35413091, 2022). "Western blot analyses confirmed specific inhibition of targeted DDR pathways in the analyzed bladder cancer cell lines, i.e., drugs blocked DNA-PK phosphorylation at Ser2056 and the ATR downstream mediator CHK1 at Ser317." (PMID 35740300, 2022). "As such, the current study provides a rationale for testing ATR inhibitors in combination with gemcitabine in patients with bladder cancer, particularly for patients with advanced and/or metastatic disease." (PMID 35413091, 2022). "This study aims at assessing the impact of a potent and selective DNA-PK inhibitor (DNA-PKi: AZD7648) and an ATR inhibitor (ATRi: Ceralasertib) to foster radiosensitization of bladder cancer cells in vitro." (PMID 35740300, 2022). "This study aims at analyzing the impact of the pharmacological inhibition of DNA damage response (DDR) targets (DNA-PK and ATR) on radiosensitization of bladder cancer cell lines of different molecular/histological subtypes." (PMID 35740300, 2022). "Thus, the individual molecular background of bladder cancer patients, including biallelic ATR or PRKDC deficiencies, should be considered in future studies, which may finally allow treatment of patients with a single drug but with comparable efficacy of tumor cell lethality." (PMID 35740300, 2022). "The ATR inhibitor AZD6738 enhanced gemcitabine activity in bladder cancer cells by inhibiting gemcitabine-induced DNA damage response." (PMID 35413091, 2022). "Here, the efficacy of combining gemcitabine with the novel ATR inhibitor AZD6738 was investigated in vitro in three bladder cancer cell lines (J82, T24, and UM-UC-3 cells)." (PMID 35413091, 2022). "In this research, CDDP-resistant bladder cancer cells shows increased chromatin-binding ATR and Cdc6 compared to parent cells." (PMID 27246979, 2016). "To determine the clinical relevance of ATR's role in bladder cancer treatment, we assessed a gene expression dataset of 165 bladder cancers [GSE13507]." (PMID 26657501, 2016). "We have identified a potential small-molecule inhibitor of ATR-Chk1 signaling as an attractive treatment for advanced bladder cancer." (PMID 26657501, 2016). "Here, we demonstrate that inhibition of ATR-Chk1 pathway with the potent inhibitor WYC0209 sensitizes bladder cancer cells to cisplatin." (PMID 26657501, 2016). "More importantly, Cdc6 promotes CDDP resistance in bladder cancer cells by collaborating with ATR signal pathway." (PMID 27246979, 2016). "Our findings collectively suggest that ATR-Chk1 is a target for improving the efficacy of cisplatin in bladder cancer." (PMID 26657501, 2016). "We show here that inhibition of ATR-Chk1 pathway provides marked improvement in the response to cisplatin in bladder cancer." (PMID 26657501, 2016). "ATR inhibitors have been used in clinical trials in combination with radiation or chemotherapeutics; however, their effects against bladder cancer remain unclear." (PMID 35413091, 2022).